MIA (MIA SH3 domain containing)
Diseases named in the same sentence as MIA in open-access papers (continued):
Sharing a sentence is not in itself a finding about the gene and the disease.
osteoarthritis (1 paper, 2023). A noninflammatory degenerative joint disease occurring chiefly in older persons, characterized by degeneration of the articular cartilage, hypertrophy of bone at the margins and changes in the synovial membrane. "MIA/CD-RAP-deficient mice develop milder osteoarthritis than wildtype mice." (PMID 36672165, 2023). "In that specific study, we revealed an enhanced chondrocytic proliferation in the MIA/CD-RAP-null mice, depicted by enhanced regeneration after osteoarthritis induction." (PMID 36672165, 2023). "In this study, we wanted to assess the effect of this MIA/CD-RAP inhibitory peptide during osteoarthritis development." (PMID 36672165, 2023). "Finally, we investigated the pharmacological targeting of MIA/CD-RAP as a potential strategy to modulate osteoarthritis onset and development." (PMID 36672165, 2023). "The mice treated with the MIA/CD-RAP inhibitory peptide showed less osteoarthritis development." (PMID 36672165, 2023). "Importantly, we could also reveal enhanced chondrocytic regeneration in the MIA/CD-RAP-null mice and an ongoing reduction in OA scores, making MIA/CD-RAP a very interesting target of disease-modifying osteoarthritis drugs." (PMID 36672165, 2023). "Given the role of MMP13 as a major driver of osteoarthritis, we wanted to assess the role of MIA/CD-RAP-dependent MMP13 regulation under inflammation." (PMID 36672165, 2023). "Our findings revealed MIA/CD-RAP as a new regulator of MMP13 and highlighted its role as a potential new target for osteoarthritis therapy." (PMID 36672165, 2023). "Finally, osteoarthritis was surgically induced via DMM in C57BL/6 mice, and the animals were treated with an MIA/CD-RAP inhibitory peptide by subcutaneously implanted pellets." (PMID 36672165, 2023).
vitiligo (1 paper, 2020). Generalized well circumscribed patches of leukoderma that are generally distributed over symmetric body locations and is due to autoimmune destruction of melanocytes. "MIA protein causes complete vitiligo-like depigmentation by direct injection in the tail of mice, operating a melanocythorragic effect on the melanocytes." (PMID 32974361, 2020). "In this study, we present an animal model of vitiligo on the basis of the ability of the MIA protein to induce vitiligo-like lesions." (PMID 32974361, 2020). "In this study, we developed a mouse model of vitiligo on the basis of the action of the MIA protein, characterized by the appearance of clear zone of depigmentation determined by the detachment of melanocytes from the basal membrane." (PMID 32974361, 2020). "In order to investigate the melanocytorrhagic hypothesis, we established a mouse model of vitiligo on the basis of the sole action of the MIA protein." (PMID 32974361, 2020). "Based on our previous demonstration of the presence of MIA protein in the skin of patients affected by vitiligo and on the ability to create a vitiligo-like depigmentation in mice, this molecule could probably be considered as a key part of the very complex puzzle of vitiligo pathogenesis." (PMID 32974361, 2020).
tumor (21 papers, 2005 to 2025). "The expression of secreted protein‐coding genes, including MDK, HGF, RARRES2, GDF15, IL6 and MIA, was concentrated in the tumour cell‐enriched region, thus confirming the expression specificity of these signalling molecules." (PMID 38318640, 2024). "Three hub genes (IL17C, TNFSF15, and MIA) related to tumor immunity and metastasis were identified by WGCNA, and the abnormal expression of each hub gene in ESCA has a poor prognosis, especially in patients with high expression (P < 0.05)." (PMID 36936375, 2023). "On this basis, IL17C, TNFSF15, and MIA which were related to tumor immunity, invasion, and metastasis were identified." (PMID 36936375, 2023). "The expressions of IL17C, TNFSF15, and MIA in tumor tissues were significantly different from those in adjacent tissues." (PMID 36936375, 2023). "Overexpression of MIA enhances tumor cell survival and promotes activation of the PI3K/mTOR signaling pathway." (PMID 34441956, 2021). "MIA and MIA2 have been reported to be associated with cell migration, tumor invasion, and lymph node metastasis in OSCC, however, the role of MIA and MIA2 in OED is the subject of future research." (PMID 34441956, 2021). "In this study, 477 tumor specimens were subjected to immunohistochemical screening to evaluate MIA gene family expression." (PMID 27145272, 2016). "Although MIA gene family members serve several tumor-related functions, to our knowledge, this is the first report to subject a variety of human malignancies to semi-comprehensive immunohistochemical MIA gene family expression profiling." (PMID 27145272, 2016). "Although MIA gene family members have several tumor-related functions, their detailed roles in malignancies remain poorly elucidated." (PMID 27145272, 2016). "Although OTOR expression is highly restricted to healthy eyes, cochlea, and cartilage, other members of the MIA gene family have several tumor-related functions." (PMID 27145272, 2016). "In the present study, we examined expression of MIA in Nf1-deficient mouse cartilage, in human cutaneous and plexiform neurofibromas and MPNSTs, and in sera of NF1 patients with these tumours." (PMID 21726432, 2011). "Patients with elevated MIA-, S100B- or LDH-levels had a 6.5-fold, 4.2-fold or 6.1-fold higher mortality risk compared to patients with normal tumor markers." (PMID 21935432, 2011). "It thus appears likely that MIA expression in NF1 tumours is also regulated by SOX9, as this transcription factor was reported to be required for the survival of MPNST cells." (PMID 21726432, 2011). "The exact biological functions of MIA are still unclear, but recent evidence indicates an important role of MIA in tumor progression and metastasis." (PMID 15710044, 2005). "The miR-18a/low tumours had higher expression of the luminality-associated genes like ESR1, GATA3, FOXA1, XBP1 and TFF1 and a lower expression of the basality-associated genes such as KRT18, KRT17, FOXC1, ANLN, STIL and MIA (p < 0.05)." (PMID 38786043, 2024). "Furthermore, when MIA2 is co-expressed with MIA, the overlap of integrin-mediated MIA- and MIA2-associated signaling further promotes tumor progression." (PMID 34441956, 2021). "Thus, this study ZnPcS4 PS drug was conjugated onto the surface of amine functionalized AuNPs, which had Anti-MIA antibodies bound to its surface in order to actively improve PS drug delivery and increase its uptake and absorption within MM target tumor cells." (PMID 31692760, 2019). "Members of the MIA gene family appear to perform several tumor-related functions." (PMID 27050375, 2016). "However, the role of MIA gene family as tumor markers in various human malignancies remains controversial." (PMID 27145272, 2016). "In addition, overexpression of MIA in melanoma cells induces an aggressive tumor type by enhancing the metastatic potential." (PMID 15710044, 2005).
tumor (continued). "But in ESCAs, the expression of MIA was increased in moderately or poorly differentiated tumor tissues, and patients with high differentiated tumors lived longer than that middle-low differentiated patients, which indicates that MIA may have different roles according to the different tumor." (PMID 36936375, 2023). "In addition, overexpression of MIA also inhibits the apoptosis of tumor cells." (PMID 34441956, 2021). "Thus, the conjugation of a MM tumor-targeting antibody (Ab) such as Anti-MIA, onto a sulpho pure ZnPcS PS carrying AuNPs surface would seem highly desirable, in order to promote drug solubility, as well as active MM tumor targeting uptake in order to enhance PDT seems promising." (PMID 31692760, 2019). "Compared with non-tumor esophageal epithelium, ESCC tissues were more likely to exhibit subcellular MIA gene family expression." (PMID 27145272, 2016). "Subcutaneous coimplantation experiments further confirmed that, compared with the control group (Vector-LOXL2.HPSCs+MIA PaCa-2 group), the LOXL2-OE group (OE-LOXL2.HPSCs+MIA PaCa-2 group) exhibited significant tumor-promoting effects, with tumors displaying greater linear ECM alignment." (PMID 40425551, 2025). "Besides tumor cells, MIA/CD-RAP is abundantly expressed and secreted by chondrocytes and cartilaginous tissues and is here referred to as CD-RAP (cartilage-derived retinoic-acid-sensitive protein)." (PMID 36672165, 2023). "MIA and MIA2 are also frequently expressed in OSCC, in which both promote tumor progression." (PMID 34441956, 2021). "As the MIA gene family members are also secretory proteins, TANGO might be useful as a tumor marker detectable in the serum, saliva, urine, ascites and pleural fluid, and other samples." (PMID 30115834, 2018). "Reportedly, MIA and MIA2 are involved in OSCC tumor progression." (PMID 30115834, 2018). "Expression levels of MIA gene family in primary tumor and metastatic sites remained unchanged (data not shown)." (PMID 27145272, 2016). "When stratifying EC patients based on tumor size, five proteins were significantly increased in patients with tumors larger than 2 cm: endoglin (p = 0.03), FAP (p = 0.001), HB-EGF (p = 0.04), MIA (p = 0.01), and VEGF-A (p = 0.02), when compared to patients with smaller tumors (≤ 2 cm)." (PMID 39511039, 2024).
cancer (9 papers, 2005 to 2024). A tumor composed of atypical neoplastic, often pleomorphic cells that invade other tissues. "The MIA gene family is considered a useful marker for many types of cancers, and its upregulation has been associated with shorter progression free survival times." (PMID 32756008, 2020). "In addition, MIA gene family expression was also associated with a poor prognosis among cancer patients." (PMID 27145272, 2016). "Although additional detailed and large-scale examinations will be fundamental to determining the importance of MIA gene family members in cancers, our findings indicate that these proteins are alternative and efficacious diagnostic and treatment targets in human cancers." (PMID 27145272, 2016). "MIA is a secretory protein that promotes cell separation, migration, invasion, and metastasis and inactivates cancer cell apoptosis." (PMID 38902713, 2024). "In pancreatic tissues, MIA was predominantly localized in malignant cells and in tubular complexes of cancer specimens, whereas normal ductal cells, acinar cells and islets were devoid of MIA immunoreactivity." (PMID 15710044, 2005). "The expression of MIA and MIA2 was only rarely observed in the keratinized layer in OED specimens, but a more pronounced expression was observed in the cancer pearl of OSCC." (PMID 34441956, 2021).
MIA also shares sentences with these, for which no sentence is quoted: adenocarcinoma (1 paper); adenoma (1); cervical squamous cell carcinoma (1); colorectal adenocarcinoma (1); familial colorectal cancer (1); gastric adenocarcinoma (1); gastric cancer (1); hematological disease (1); metastasis (1); metastatic disease (1); neuroectodermal tumors (1); non-small cell lung carcinoma (1); oral squamous cell carcinoma (1); ovarian carcinoma (1); Partington syndrome (1); Pfeiffer syndrome (1); prostatic adenocarcinomas (1); small cell carcinoma (1); testicular seminoma (1).